IL1B (interleukin 1 beta)
Diseases named in the same sentence as IL1B in open-access papers (continued):
Sharing a sentence is not in itself a finding about the gene and the disease.
penile squamous cell carcinoma (1 paper, 2025). "Immunohistochemistry (IHC) analysis of eight cytokines (IL-1A, IL-1B, IL-2, IL-6, IL-12, TGF-β1, TNF-α and IFN-γ) was performed in paired tumour tissues and corresponding negative surgical margins from 94 patients with penile squamous cell carcinoma." (PMID 41465261, 2025).
penile tumour (1 paper, 2025). "Transcriptomic analyses have demonstrated the elevated mRNA expression of IL-1A, IL-1B, IL-6, IFN-γ, and TGF-β1 in penile tumour tissue, with a positive correlation between IFN-γ levels and tumour stage." (PMID 41465261, 2025).
peritoneal adhesion (1 paper, 2018). "In this study, we demonstrated that fibrin induced IL-1β, IL-6, TNFα and VEGF-A expression in PMCs, which could be attenuated by QLT-0267, and that QLT-0267 treatment could ameliorate post-surgical peritoneal adhesion." (PMID 29930281, 2018).
Perthes disease (1 paper, 2023). "Previous studies have demonstrated that certain cytokines, including IL-6, IL-1β, and tumor necrosis factor (TNF)-α, are overexpressed in individuals with Perthes disease." (PMID 37303951, 2023).
pilocytic astrocytoma (1 paper, 2020). Pilocytic astrocytoma is a rare subtype of low-grade glioma of the central nervous system characterized by a well circumscribed, often cystic, brain tumor with a discrete mural nodule and long, hair-like projections that extend from the neoplastic astrocytes. "Secondly, it has been shown in a pilocytic astrocytoma cell model that mediators of inflammation such as interleukin-1b (IL-1b) did reduce cell growth via induction of senescence-associated secretory phenotype expression." (PMID 32548671, 2020).
placental insufficiency (1 paper, 2023). Failure of the placenta to deliver an adequate supply of nutrients and oxygen to the fetus. "Maternal serum abundance of IL-1β was elevated in third trimester pregnancies affected by placental insufficiency and FGR, compared to uncomplicated pregnancies." (PMID 36994431, 2023).
pleural tumor (1 paper, 2023). "Tryptase AB1 and interleukin-1-beta released by mast cells intensify pleural fluid production and tumor progression by augmenting vascular permeability and activating NF-kB in pleural tumor cells." (PMID 37256127, 2023).
pneumonic pasteurellosis (1 paper, 2016). Bovine respiratory disease found in animals that have been shipped or exposed to cattle recently transported. "In addition, the expression of IL1-β and TNF-α were elevated in the respiratory airways and lung lesions of diseased calves with pneumonic pasteurellosis." (PMID 27547520, 2016).
pollen allergies (1 paper, 2012). "In grass pollen allergies, a state of chronic inflammation in the upper airways is reminiscent of allergen-induced activity of the innate immune system, which can be analyzed by the presence of TNF-α and IL-1β on day 1 in allergen-induced in vitro PBMC cultures." (PMID 22315506, 2012).
post-concussion syndrome (1 paper, 2024). The organic and psychogenic disturbances observed after closed head injuries (HEAD INJURIES, CLOSED). "[IL1B on MOG] levels also correlated with the clinical course of a post-concussion syndrome case." (PMID 38559234, 2024).
pouchitis (1 paper, 2024). Acute inflammation in the intestinal mucosa of the continent ileal reservoir (or pouch) in patients who have undergone ileostomy and restorative proctocolectomy (proctocolectomy, restorative). "A cytokine storm (IL-1beta, IL-6, IL-8 and TNF-alpha), with the gain of function mutations in IL1β and the disruption of intestinal barrier, complete the picture of mucosal inflammation in pouchitis." (PMID 39770958, 2024). "Furthermore, IL1B/LYZ+ myeloid cells are responsible for reduced responses to vedolizumab in patients with pouchitis." (PMID 39770958, 2024).
primary ciliary dyskinesia (1 paper, 2017). A rare, genetically heterogeneous, primarily respiratory disorder characterized by chronic upper and lower respiratory tract disease. "The non-normalized CXCL8 and IL-1β levels released by peripheral blood mononuclear cells (PBMCs) from adult controls (Ad CO), pediatric controls (Ped CO) and patients with primary ciliary dyskinesia (PCD)." (PMID 29018439, 2017).
primary effusion lymphoma (1 paper, 2024). A large B-cell lymphoma located in the body cavities, characterized by pleural, peritoneal, and pericardial fluid lymphomatous effusions and that is always associated with human herpes virus-8 (HHV-8). "Primary effusion lymphoma (PEL) cells show evidence of NRLP3 inflammasome activation, such as the presence of active caspase-1 and cleavage of pro-IL-1β and pro-IL-18." (PMID 38397043, 2024).
progeria (1 paper, 2019). "We examined a larger set of inflammatory cytokines in an additional progeria cells (AG03513) after transient expression of hTERT and found reduced mRNA levels of IL6, IL8, IL1B, and GM‐CSF." (PMID 31152494, 2019).
progressive sensorineural hearing loss (1 paper, 2025). "We identified a ZNF334 truncation mutation (p.Thr399fs) in a rare case of late-onset cold-induced autoinflammatory disease with elevated TNF-α, IL-1β, IL-6, and extracellular heat shock protein 90 (eHsp90) plasma levels and progressive sensorineural hearing loss." (PMID 41168503, 2025).
prurigo (1 paper, 2020). A name applied to several itchy skin eruptions of unknown cause. "The histological examination of prurigo samples presented an accumulation of neuropeptides that upregulated the production of many proinflammatory cytokines (interleukin (IL)-1α, IL-1β, and IL-8)." (PMID 33182351, 2020).
Pyoderma (1 paper, 2026). Any manifestation of a skin disease associated with the production of pus. "In a murine pyoderma model, bentonite pre-treatment of S. pseudintermedius prevented lesion development, reduced bacterial burden, and downregulated cutaneous expression of TNFα, IL-1β, and IL-13, findings that were corroborated by histological improvements." (PMID 41576001, 2026).
radiation proctitis (1 paper, 2025). "For example, emodin could inhibit inflammation by restraining the NF-κB pathway, resulting in a decrease in proinflammatory gene expression, like IL-1β and NF-κB in acute radiation proctitis for mice." (PMID 39858180, 2025).
radicular cyst (1 paper, 2018). "We found that the expression levels of IL-1α and IL-1β in the radicular cyst and normal control groups were very low; the average expression levels of IL-1β in those two groups were only 0.0017 and 0.0016 μg/mg total protein, respectively." (PMID 30012121, 2018).
radiculopathy (1 paper, 2016). Disease involving a spinal nerve root (see spinal nerve roots) which may result from compression related to intervertebral disk displacement; spinal cord injuries; spinal diseases; and other conditions. "IL-1β, TNF-α and other pain-mediating chemicals released from the NP can irritate dorsal root ganglions, contributing to functional and structural nerve damage, radiculopathy and muscle weakness in vivo." (PMID 27689996, 2016).
renal adenocarcinoma (1 paper, 2021). "We demonstrated that sunitinib increased IL-1β, IL-6,IL-8 and IL-18 expression in cardiomyocytes and renal adenocarcinoma cells and that polydatin is able to significantly reduce their expression." (PMID 34178667, 2021).
Renal atrophy (1 paper, 2022). Atrophy of the kidney. "Likewise, the receptor of IL-1β is associated with IRAK-M (Interleukin 1 Receptor associated Kinase 3Macrophages), a biomarker for renal atrophy and interstitial fibrosis." (PMID 35684085, 2022).
renal hypouricemia (1 paper, 2021). "Therefore, increased post-exercise urinary urate excretion in renal hypouricemia patients induces IL-1β production in renal tubule cells and IL-1β may stimulate the sensory nerves around the cortical tubules to stimulate the medulla oblongata nucleus and cause nausea and vomiting." (PMID 34944661, 2021).
reovirus infection (1 paper, 2018). "Up-regulated expression of AP-1 and STAT after reovirus infection can promote the expression of proinflammatory cytokines and inflammatory cytokines, such as TNFα, IL-12/IL-1β." (PMID 29562634, 2018).
Respiratory insufficiency (1 paper, 2022). "In any case, treatment of COVID-19 patients with respiratory insufficiency and hyper inflammation with IL-1 inhibitors was associated with a significant reduction of mortality, indicating that at least during severe COVID-19 the overall effect of IL-1β is detrimental." (PMID 35025963, 2022).
reticulum cell sarcoma (1 paper, 2023). An antiquated term that refers to a non-Hodgkin lymphoma composed of diffuse infiltrates of large, often anaplastic lymphocytes. "Compounds 154, 155, 157 and 158 from Callicarpa arborea showed potent inhibitory effects against the NLRP3 inflammasome by inhibiting Casp-1 activation and IL-1β in reticulum cell sarcoma cells." (PMID 37375299, 2023).
Rett syndrome (1 paper, 2013). A severe neurodevelopmental disorder affecting the central nervous system. "Recently, we have demonstrated that CNF1 can significantly decrease the levels of IL-1β in pure astrocytic cultures and the level of IL-6 in a mouse model of Rett's syndrome." (PMID 23738020, 2013).
Rickettsiosis (1 paper, 2022). A group of infectious diseases that is caused by Rickettsia. "In contrast, transfer of Il-1β−/− BMDMs had an overall lesser effect on the severity of rickettsiosis, as evidenced by a lower mortality rate, smaller spleen size, and lower bacterial burden in Cl2MBP-treated WT mice, which is in agreement with our IL-1β Ab neutralization data." (PMID 35130729, 2022). "in vivo, IL-1α or IL-1β function was neutralized via tail vein (intravenous [i.v.]) injection with anti-IL-1α, anti-IL-1β, or anti-IgG-isotype control antibodies (Abs) into C57BL/6J WT mice in our established model of mild rickettsiosis (LD25; ∼105 PFU)." (PMID 35130729, 2022).
Rotavirus infection (1 paper, 2025). Infection with any of the rotaviruses. "Moreover, rotavirus infection elicited inflammatory responses, as shown by the significant IL-1β gene expression and production." (PMID 40368896, 2025).
salivary gland disease (1 paper, 2020). "Another study found that in a co-culture of NOD mice salivary gland acinar cells (SGAC) and B-lymphocyte (an in-vitro model of salivary gland disease in SS), there was a significant increase in production of cytokines IL-6 and IL-1β by B-lymphocytes and increased phosphorylation of STAT3 in SGAC." (PMID 32849505, 2020).
salpingitis (1 paper, 2025). Acute or chronic inflammation of the fallopian tube. "Estrogen and progesterone can protect against LPS-induced mouse salpingitis by inhibiting the activation of the NF-κB, MAPK, and PI3K/Akt signaling pathways and suppressing the expression of the inflammatory factors IL-1β, TNF-α, IL-10, and mBD-2." (PMID 40604711, 2025). "In this study, the effects of E2 and P4 on the expression of IL-1β, TNF-α, IL-10, and mBD-2 in LPS-stimulated fallopian tube epithelial cells, as well as the potential mediation of postinjury salpingitis through the NF-κB, MAPK, and PI3K/Akt pathways, were investigated." (PMID 40604711, 2025).
seborrheic dermatitis (1 paper, 2020). A chronic, inflammatory skin disorder that affects the scalp, central face and skin folds; it is characterized by scaling and itching. "Activation of NLRP3 depends on Dectin-1 and leads to high expression of caspase-1-dependent IL-1β in dendritic cells of patients with seborrheic dermatitis." (PMID 33552997, 2020). "Human studies have shown that cytokine levels (IL-1α, IL-1β, IL-2, IL-4, IFN-γ, IL-10, and IL-12) in the skin of individuals with seborrheic dermatitis and Malassezia folliculitis were higher than levels in the skin of healthy volunteers." (PMID 33552997, 2020).
secondary pulmonary hypertension (1 paper, 2016). "The most important inflammatory cytokines associated with primary or secondary pulmonary hypertension are IL-1β and IL-616." (PMID 27886226, 2016).
seminoma (1 paper, 2023). A radiosensitive malignant germ cell tumor found in the testis (especially undescended), and extragonadal sites (anterior mediastinum and pineal gland). "In agreement with this hypothesis, an overexpression of IL-1β, IL-6 and TNF-α has been reported in seminoma." (PMID 37371875, 2023).
sensitization (1 paper, 2022). "Importantly, we conclude from our study that IL-1β and TSLP are two independent factors promoting allergic sensitization and atopic march." (PMID 36050303, 2022).
sensory impairment (1 paper, 2020). "Secondly, more importantly, the expression of GFAP and inflammatory cytokines IL‐1β, IL‐6, and TNF‐α were increased both in PD patients with and without sensory impairment." (PMID 31828965, 2020).
Sensory neuropathy (1 paper, 2018). Peripheral neuropathy affecting the sensory nerves. "In line with this concept, in the present study, diabetic mice presented enhanced levels of IL-1β and TNF-α in the spinal cord, while MSC treatment inhibited this upregulation, in parallel with its effects on behavioral sensory neuropathy." (PMID 29933760, 2018).
skin changes (1 paper, 2015). "The opposing effects of OSM and IL-1β compared with IL-17 and IL-22 on chemerin production in keratinocytes suggests different roles for the former in regulating chemerin-mediated skin changes." (PMID 25659101, 2015).
skin infectious diseases (1 paper, 2021). "The up-regulation of Mincle and IL1B in our study may suggest activation of the host immune responses and protection of giant pandas from skin infectious diseases." (PMID 33639852, 2021).
skin pigmentation disorder (1 paper, 2025). A pigmentation disease that involves the zone of skin. "In essence, TLNVs mitigate the expression of pro-inflammatory cytokines TNF-α and IL-1β, ameliorate the inflammatory milieu, and foster melanin degradation through an autophagy pathway governed by LC3B and P62, underscoring its prospective utility in ameliorating skin pigmentation disorders." (PMID 40735705, 2025).
skin toxicity (1 paper, 2022). "In addition, the mean serum IL-1β level at 24 h after cycle 1 in patients with skin toxicity was lower than that in patients without skin toxicity." (PMID 36269747, 2022).
skin ulceration (1 paper, 2025). "Both NK and CD8+ T cells have been shown to kill Leishmania protozoa-infected cells, leading to the release of DAMPs, activation of NLRP3 inflammasomes, and IL-1β, which exacerbate skin ulceration." (PMID 39319843, 2025).
small intestinal tumors (1 paper, 2025). "Liu et al16 found the quantity of inflammatory mediators (IL-6, IL-1β, and TNF-α) in the small intestinal tumors of Apcmin/+ mice was higher than that in the control group." (PMID 40241344, 2025).
small-fiber neuropathy (1 paper, 2021). "After IL-1β-highly responsive clone (6D cells) from noninvasive MCF-7 BC cells were stimulated by IL-1β, the expression of CDKN1A/p21, TP63, small-fiber neuropathy (SFN), and especially BIRC3, was upregulated, which made BC cells resistant to doxorubicin." (PMID 34602858, 2021).
social phobia (1 paper, 2023). An anxiety disorder characterized by an intense, irrational fear of one or more social or performance situations in which the individual believes that he or she will be scrutinized by others. "We also observed statistically significant associations between SOD2 rs4880 and obsessive–compulsive symptoms, PON1 rs705381 and social phobia, IL1B rs1071676 and AUDIT scores, and IL6R rs2228145 and compulsions in alcohol-addicted patients." (PMID 38275640, 2023).
soft tissue tumours (1 paper, 2022). "IL1β has also been shown to promote infiltration of monocytes and macrophage differentiation in soft tissue tumours." (PMID 36230739, 2022). "Once tumour cells are disseminated in soft tissues, inhibiting IL1β signalling with Anakinra has been shown to reduce myeloid cell accumulation in E0771 soft tissue tumours." (PMID 36230739, 2022). "In addition to its direct anti-metastatic properties, IL1β plays a central role in regulating immunity, and it has recently become apparent that IL1β within the tumour microenvironment is important for recruiting anti-tumour immune cells, especially in soft tissue tumours." (PMID 36230739, 2022).
sporadic CJD (1 paper, 2021). "In line with this, increased levels of inflammatory cytokines including IL-8, CCL2, TGFβ, TNF and IL-1β have been found in the CSF of sporadic CJD cases, with increased IL-1β levels correlating with the number of activated microglia at early stages of the disease." (PMID 33776778, 2021).
squamous cell tumors of the (1 paper, 2025). "The study by Douglas Hanahan and colleagues found that squamous cell tumors of the cervix and skin, driven by Human Papillomavirus type 16 (HPV16), release four immunomodulatory factors ‒ IL-1α, IL-1β, IL-33, and IL-36β ‒ into the bloodstream." (PMID 41418390, 2025).
staphylococcus aureus pneumonia (1 paper, 2023). An pneumonia caused by infection with Staphylococcus aureus. "Attenuated IL-1β production was also linked with Staphylococcus aureus pneumonia exacerbation in another study." (PMID 36692289, 2023).
Stillbirth (1 paper, 2022). Death of the fetus in utero after at least 22 weeks of gestation. "The levels of IL-6 (P = 0.02) and IL-1β (P = 0.01) were significantly higher in the serum of stillbirth sows than that in normal sows." (PMID 36741405, 2022). "As we expected, the serum levels of TLR4, IL-6 and IL-1β had higher concentration in the stillbirth sow group." (PMID 36741405, 2022).
structural epilepsy (1 paper, 2019). A type of epilepsy that is conceptualized as having a distinct structural brain abnormality that has been demonstrated to be associated with a substantially increased risk of epilepsy in appropriately designed studies. "In order to compare levels of IL-1β in serum samples of epileptic to those of healthy dogs, Kruskal–Wallis test for unequal sample size was performed and showed that both idiopathic as well as structural epilepsy dogs had higher levels of IL-1β in serum than healthy dogs (p = 0.003)." (PMID 31208341, 2019).
subacute sclerosing panencephalitis (1 paper, 2024). A chronic progressive encephalitis that develops a few years after measles infection and presents with a demyelination of the cerebral cortex. "Positive correlations were found between S100B and TNF-α, S100B and IL-1β, and NF-H and soluble TNF receptor 1 in subacute sclerosing panencephalitis." (PMID 39272777, 2024).
systemic fungal infections (1 paper, 2015). "It is well documented that IL-1β secretion requires the function of the inflammasome and that both the inflammasome and IL-1β are important in limiting systemic fungal infections." (PMID 25629406, 2015).
tapeworm infection (1 paper, 2022). "In addition, the gene expression profile of the pro- and anti-inflammatory cytokines (TNF-α, IL-1β, IL-6 and IL-10) was evaluated by Real-Time PCR to determine the immune response within the CNS to the tapeworm infection." (PMID 35286352, 2022).
temporomandibular joint disorder (1 paper, 2025). Any condition affecting the anatomic and functional characteristics of the temporomandibular joint. "The COMT, HTR2A, MMPs, IL-1β, IL-6, TNF-α and ESR1 are known to influence the pain perception, inflammation, and joint integrity in temporomandibular joint disorders." (PMID 40291793, 2025).
testicular disease (1 paper, 2021). "In testicular-inflammation, cytokines such as TNF-α, IL-1α and IL-1β are produced in significant levels, and are particularly known to aggravate testicular disease progression, and subsequent death." (PMID 33565293, 2021).
tetanus (1 paper, 2018). A serious infectious disorder that follows wound contamination by the Gram-positive bacterium Clostridium tetani. "In cultures stimulated with CMV, EBV, influenza and tetanus peptides, the CD4+ T‐cell count correlated with IL‐1β (P = 0.045) and CD8+ T‐cell count with IFNγ (P = 0.013) and IL‐1β (P = 0.012)." (PMID 30323928, 2018).